CRTC1 (CREB regulated transcription coactivator 1)
Diseases named in the same sentence as CRTC1 in open-access papers (continued):
Sharing a sentence is not in itself a finding about the gene and the disease.
depression (13 papers, 2016 to 2025). "Here, the CRTC1 SNP rs6510997 was found to be negatively associated with BMI in women with a lifetime diagnosis of depression." (PMID 35242012, 2022). "In line with CRTC1’s role in neuroplasticity processes, as well as the involvement of CREB and BDNF in rodent models of depression, increasing evidence suggests that CRTC1 is implicated in the pathogenesis of MDD." (PMID 35242012, 2022). "Thus, the Crtc1 knock-out (Crtc1−/−) mouse was shown to be a useful model to study the pathways and mechanisms linking metabolic diseases with depression and to understand associated resistance to classic antidepressants, in particular to fluoxetine." (PMID 36224260, 2022). "In this study, BDNF was chosen as the downstream molecular target underlying the protecting effects of ARN-3236 against chronic stress, as BDNF is a very well-known member implicated in the pathogenesis of depression, and moreover, its biosynthesis is closely controlled by CRTC1 and CREB." (PMID 33519490, 2020). "CRTC1, through the regulation of BDNF, has been implicated in multiple neurodegenerative and neuropsychiatric conditions, but the evidence for major depressive disorder is presented below." (PMID 36731029, 2023). "The putative role of CRTC1 in the alteration of brain energy homeostasis observed in depression is also discussed." (PMID 35242012, 2022). "This study provides new insights on Crtc1’s and MeS’s relationship to MD and establishes depression-related markers with clinical potential." (PMID 36224260, 2022). "Seven models that matched depression from different approaches (HDAC2 forebrain KO, APPsa knockin, stress portrait, ACHE variant, HD R6/1 transgenic, CRTC1 KO, and HTRA2 KO) were analyzed and common up and down regulated genes with depression were identified." (PMID 34997033, 2022). "We discuss the role of CRTC1 downregulation in mediating chronic stress-induced depressive-like behaviors, and antidepressant response in the light of the previously characterized Crtc1 knockout mouse model of depression." (PMID 35242012, 2022). "shRNA-mediated suppression of CRTC1 in the hippocampus directly resulted in depression-like behavior." (PMID 35625877, 2022). "Ni and colleagues used injections of AAV9 in the hippocampus to study the role of CRTC1 (CREB regulated transcription coactivator 1 protein) in depression." (PMID 35625877, 2022). "ARN-3236, a selective inhibitor of SIK2, induced significant antidepressant-like effects in both the CSDS and CUMS models of depression by acting on the hippocampal CRTC1-CREB-BDNF pathway and adult hippocampal neurogenesis." (PMID 35242012, 2022). "Conversely, AAV-short hairpin RNA (shRNA)-mediated knockdown of hippocampal SIK2 or genetic knockout of Sik2 protect mice against both chronic stress models of depression with antidepressant-like effects that require the downstream CRTC1-CREB-BDNF pathway." (PMID 35242012, 2022). "In a chronic stress-induced depression model in mice, the levels of salt-inducible kinase 2, which is a kinase of CRTC1, was increased in the hippocampus, resulting in inhibition of CRTC1/CREB-regulated BDNF expression." (PMID 34977362, 2021). "Collectively, these findings implicate Agmat in the depressive-like phenotype of Crtc1−/− mice, refine current understanding of the agmatinergic system in the brain and highlight its putative role in major depression." (PMID 27404284, 2016). "In conclusion, our results provide evidence for the involvement of the agmatinergic system in the Crtc1−/− mouse model of depression, and lend support to previous reports of the antidepressant properties of agmatine." (PMID 27404284, 2016). "The deletion of CREB-regulated transcription coactivator 1 (CRTC1) has the capacity to induce impulsive aggressiveness, behavioral despair, psychomotor retardation, increased emotional response to stressful events, anhedonia, and depression-related behaviors." (PMID 31406011, 2019).
depression (continued). "Chronic social defeat-induced stress (CSDS) and chronic mild stress (CMS) are both used to model depression in mice and induced SIK2 in the hippocampus and prefrontal cortex and, in agreement, also reduced nuclear CRTC1." (PMID 36731029, 2023). "In 2019, we have reported that chronic stress-induced depression was accompanied by increased SIK2 expression and decreased nuclear CRTC1 translocation and CRTC1-CREB binding in the hippocampus." (PMID 33519490, 2020). "It has been well demonstrated that CRTC1, BDNF and neurogenesis play critical roles in not only depression but also many other neurological disorders, such as Alzheimer's disease, Parkinson's disease, stroke and epilepsy." (PMID 33519490, 2020). "In this study, we showed for we believe the first time a link between downregulation of the CRTC1–CREB pathway and alteration of the agmatinergic system in the context of a rodent model of depression." (PMID 27404284, 2016).
Alzheimer disease (10 papers, 2016 to 2025). A progressive, neurodegenerative disease characterized by loss of function and death of nerve cells in several areas of the brain leading to loss of cognitive function such as memory and language. "Synaptic activity induces CRTC1 dephosphorylation (Ser151), nuclear translocation, and CRTC1-dependent transcription in the hippocampus, which is deficient in Alzheimer's disease models." (PMID 27034888, 2016). "Specifically, NXPH1 regulates synaptic plasticity, while CRTC1 has been linked to aging-related disorders such as Alzheimer’s disease and regulates gene expression related to dendritic maturation and inflammation to promote blood–brain barrier integrity, memory, and learning." (PMID 39996777, 2025). "Its expression can be regulated by methylation, as described in Alzheimer’s disease where two CRTC1 promoter regions were found to be demethylated in the hippocampus compared to the controls." (PMID 38791368, 2024). "CRTC1 has been suggested to act as a critical role in several neurodegenerative diseases, such as Alzheimer’s disease, and Huntington’s disease." (PMID 34880207, 2021). "To test if CRTC1 was differentially expressed in our cohort, we measured CRTC1 mRNA expression levels by RT-qPCR in hippocampal samples from Alzheimer’s disease (AD) cases and controls." (PMID 27094739, 2016). "Here we report altered patterns of DNA methylation within two distinct promoter regions of CRTC1 in the human hippocampus affected by Alzheimer’s disease (AD)." (PMID 27094739, 2016). "Recently, CRTC1 has been shown to be downregulated in Alzheimer’s disease (AD)." (PMID 27094739, 2016). "For example, amyloid β prevented the expression of CRTC1/CREB-dependent neuronal genes including Bdnf, which likely resulted in hippocampal-dependent memory impairment in mouse and rat models of Alzheimer’s disease." (PMID 34977362, 2021).
Insulin resistance (10 papers, 2016 to 2025). Increased resistance towards insulin, that is, diminished effectiveness of insulin in reducing blood glucose levels. "Importantly, Crtc1–/– mice displayed insulin resistance but normal lipid levels compared to Crtc1+/+ mice at 8 months old, indicating that insulin sensitivity is earlier than plasma lipid profiles to sense fat accumulation." (PMID 33912553, 2021). "Moreover, Crtc1–/– mice were more prone to insulin resistance and dyslipidemia, as evidenced by higher levels of plasma glucose, insulin and FABP4 than wildtype mice." (PMID 33912553, 2021). "Our findings that CRTC1 may also play protective roles against dysregulation of cholesterol balance and insulin resistance further highlight the potential of CRTC1 as an alternative therapeutic target for NAFLD treatment." (PMID 27869139, 2016). "It is well known that adipocyte hypertrophy and increased adiponectin secretion in the adipose tissue are responsible for insulin resistance, consistent with the increased circulating FABP4 and insulin levels in Crtc1–/– mice observed in our study." (PMID 33912553, 2021).
melanoma (8 papers, 2011 to 2026). A malignant, usually aggressive tumor composed of atypical, neoplastic melanocytes. "The differential diagnosis includes cellular blue nevi, perivascular epithelioid cell neoplasm, melanocytic tumors with CRTC1::TRIM11 fusions, melanoma, and epithelioid malignant peripheral nerve sheath tumor." (PMID 39420989, 2024). "CRTC1::TRIM11 cutaneous tumors are an emerging subset of MITF pathway-activated neoplasms that typically present as dermal nodules and can closely mimic clear cell sarcoma or malignant melanoma." (PMID 42015602, 2026). "Routine melanoma-focused next-generation sequencing (NGS) panels do not typically include CRTC1 or TRIM11, so diagnosis often requires targeted RNA sequencing or fusion-based NGS assays." (PMID 41536371, 2025). "We then examined whether melanogenic cells in the skin could drive the phosphorylation circuits on CREB and CRTC1, employing a co-cultured model between PAM212 keratinocyte and B16F0 melanoma cells." (PMID 38164184, 2024). "Although the expression of CRTC1 and CRTC2 was observed in cultured melanocytes and/or melanoma cell lines 16, 36, CRTC1 and CRTC2 null mice did not present any skin and coat color changes 5, 6 (and personal communication)." (PMID 34815795, 2021).
colon cancer (7 papers, 2016 to 2024). "PGE2 increases cyclic adenosine monophosphate (cAMP) and intracellular Ca2+ levels through EP1 and EP2 receptors, activating PKA, which mediates CRTC1 signaling by promoting the transcriptional enhancement of tumor-promoting genes in human colon cancer cells through CREB and AP1." (PMID 39683442, 2024). "Moreover, the stable overexpression of CRTC1 significantly increases the growth of colon tumors." (PMID 39683442, 2024).
Huntington disease (6 papers, 2015 to 2024). Huntington disease (HD) is a rare neurodegenerative disorder of the central nervous system characterized by unwanted choreatic movements, behavioral and psychiatric disturbances and dementia. "Other top models were the mitochondrial gene HTRA2 knockout (that is lethal in adulthood), a modified acetylcholinesterase, a Huntington’s disease model, and the CRTC1 knockout." (PMID 34997033, 2022). "In models of Huntington's disease, mutant huntingtin protein interferes with the TORC1-CREB interaction to repress transcription of brain-derived neurotrophic factor, and also the depletion of CRTC1 contributes to Huntington's disease." (PMID 27034888, 2016).
Stroke (6 papers, 2020 to 2025). Sudden impairment of blood flow to a part of the brain due to occlusion or rupture of an artery to the brain. "CRTC1 is important in forming fear memory, stroke‐induced memory loss, schizophrenia, and LPS ‐associated working memory deficit." (PMID 40285336, 2025). "Taken together, our findings demonstrate that CRTC1 deficiency aggravates neurological deficits in mice in the early phase after stroke." (PMID 34880207, 2021). "Taken together, these results suggest that CRTC1 deletion and miR-132/212 knockdown both aggravate post-stroke neuronal damage and upregulate RBFox-1 in neurons." (PMID 34880207, 2021). "Here, we show, for the first time, changes in RBFox-1 after stroke, both in vivo and in vitro, and the role of CRTC1-miR-132/212 in these changes." (PMID 34880207, 2021). "In this study, TJAP-1 and Claudin-1 exhibited a significant increase in CRTC1 KO mice compared with WT mice, leading to BBB damage by Claudin-5/Claudin-1 dysregulation in the CRTC1 KO brain after stroke." (PMID 34880207, 2021). "In this study, we demonstrated that CRTC1 KO mice display a progressive downregulation of miR-132/212 in the early post-stroke phase, and exhibit aggravated neurological deficits and ischemic cerebral damage." (PMID 34880207, 2021). "In the acute phase after stroke, CRTC1 KO mice exhibited a statistically significant increase in TJAP-1 expression and Claudin-1 expression in comparison with WT mice." (PMID 34880207, 2021). "The impact of CRTC1 deletion on stroke outcomes led us to hypothesize that CRTC1 affects NVU integrity by regulating miR-132/212." (PMID 34880207, 2021). "Next, we examined the effect of CRTC1 knockout on mouse behavioral outcomes after stroke." (PMID 34880207, 2021). "This suggests that CRTC1 in neurons regulates TJ protein interactions in endothelial cells via a paracrine signaling mechanism to maintain BBB integrity in Neurovascular unit after stroke." (PMID 34880207, 2021).
leukemia (4 papers, 2011 to 2020). A malignant (clonal) hematologic disorder, involving hematopoietic stem cells and characterized by the presence of primitive or atypical myeloid or lymphoid cells in the bone marrow and the blood. "The repression of Crtc1, Flt3 and Mycbp was also found in leukaemia BM cells of mice with AE9a or FLT3-ITD/NPM1c+-induced AML." (PMID 27116251, 2016). "In leukaemia BM blast cells of mice with MLL-AF9-induced AML, the expression of Crtc1, Flt3 and Mycbp, but not Etv6, was significantly downregulated by co-expressed miR-22 (but not by miR-22 mutant)." (PMID 27116251, 2016).
mood disorder (4 papers, 2012 to 2024). A cognitive disorder a disturbance in which the person's mood is hypothesized to be the main underlying feature. "CRTC1 signaling has diverse functions in the brain, including roles in synaptic plasticity and mood regulation, and it is also associated with several mood disorders." (PMID 39000495, 2024). "Pathological aggression associated with defective social interactions (i.e. social withdrawal) has been found in mouse models of mood disorders (i.e. CREB-regulated transcription coactivator 1 KO mice)." (PMID 23029555, 2012). "Recent evidence collected in Crtc1−/− mice has established that not only the lack of CRTC1 induces hyperphagic obesity, but it also triggers a depressive-like phenotype, which suggests that CRTC1 plays a role in mood disorder etiology and antidepressant response." (PMID 29217834, 2017).
bladder cancer (3 papers, 2023 to 2025). "The remaining four genes, CRTC1, MB21D2, USP44 and FGFR2, may drive bladder cancer through other mechanisms of pathway crosstalk, which requires further investigation." (PMID 40768543, 2025).
Cerebral ischemia (3 papers, 2011 to 2021). Restriction of arterial blood supply to the brain associated with insufficient oxygenation to support the metabolic requirements of the tissue. "No statistically significant change was observed in penumbra between the two groups under control conditions, and cerebral ischemia led to vasculature damage in the penumbra in both CRTC1 KO and WT mice." (PMID 34880207, 2021). "Moreover, CRTC1 phosphorylation is crucial for the outcome after cerebral ischemia." (PMID 27034888, 2016). "To examine the functional role of CRTC1 in the regulation of miR-132/212 in cerebral ischemia, we generated CRTC1 KO mice using CRISPR/Cas9, and Western Blot showed that CRTC1 expression was completely absent in the mouse." (PMID 34880207, 2021).
lung carcinoma (3 papers, 2014 to 2025). "CRTC1 promotes LKB1-deficient lung cancer progression through NEDD9 transcriptional induction or glycosylated COX-2 protein activation." (PMID 40977688, 2025). "We infected human LKB1-null lung cancer A549 cells with the CRTC1-CBD-nls-GFP or GFP (control) retroviruses and observed that CRTC1-CBD-nls-GFP was predominantly localized in the nuclear compartment, while the control GFP showed diffuse cytoplasmic and nuclear signals." (PMID 34142658, 2021). "Endogenous CRTC1, CRTC2, and CRTC3 proteins showed slow migration patterns in LKB1-expressing lung cancer cells (H322)." (PMID 34142658, 2021).
schizophrenia (3 papers, 2024 to 2025). A major psychotic disorder characterized by abnormalities in the perception or expression of reality. "We demonstrated LPS‐produced CRTC1 decrease in PFC which is known to be crucial for fear memory consolidation, ischemic stroke‐produced memory deficit, and schizophrenia‐induced WM deficiency." (PMID 38353058, 2024).
Anxiety (2 papers, 2017 to 2025). Intense feelings of nervousness, tension, or panic often arise in response to interpersonal stresses. "The previous results suggest that the altered expression level of exosomal miRNA-4433a-5p in MUD is influenced by anxiety-depressive symptoms and has a low potential as a diagnostic marker for MUD, thus only validating the regulatory relationship between miRNA-184-3p and CRTC1." (PMID 40728948, 2025). "Annotation of the anxiety-related DMRs to genes revealed 183 genes, many of which were known stress-related genes such as NAV1, IGF2, GNAS, and CRTC1." (PMID 29225348, 2017).
asthma (2 papers, 2024). "Another study identified significant difference in the expression of CRTC1 and its target gene SEC14L3 in asthma, suggesting that CRTC1 plays a regulatory role in bronchial asthma or other lung diseases." (PMID 38644501, 2024). "All these pieces of evidence suggest that asthma-induced CRTC1 downregulation may affect hypothalamic metabolism and the circadian rhythm and disrupt neural plasticity, thereby predisposing individuals to mental health disorders." (PMID 39000495, 2024). "Moreover, an examination of gene expression data showed that CRTC1 and its target gene, SEC14L3, were differentially expressed in individuals with asthma, suggesting that CRTC1 may play a role in regulating conditions such as bronchial asthma or other lung diseases." (PMID 38644501, 2024).
clear cell sarcoma (2 papers, 2024 to 2026). A rare malignant neoplasm with melanocytic differentiation characterized by the presence of polygonal or spindle shaped clear cells. "In contrast, similar to EWSR1::ATF1 fusion in clear cell sarcoma, both CRTC1::TRIM11 and MITF::CREM fusions likely lead to MITF overexpression through the induction of the CREB signaling cascade." (PMID 39264472, 2024). "In both CRTC1::TRIM11 and MITF::CREM tumors, clear cell sarcoma poses the most challenging differential diagnosis due to their striking similarities." (PMID 39264472, 2024).
dyslipidemia (2 papers, 2021 to 2022). "Crtc1, a transcription cofactor regulating CREB activity, has been involved in the pathogenesis of metabolic syndrome; however, the underlying mechanism remains under debate." (PMID 33912553, 2021). "Finally, the strong resemblance between the Crtc1–/– mouse phenotype and metabolic syndrome might provide new avenues for exploring how energy deregulations relate to human MDD." (PMID 35242012, 2022). "Crtc1, a transcription cofactor regulating CREB activity, has been involved in the pathogenesis of metabolic syndrome." (PMID 33912553, 2021).
endometrial cancer (2 papers, 2020 to 2025). Primary or metastatic malignant neoplasm involving the endometrium (mucous membrane that lines the endometrial cavity). "The SNP rs2003476 in the CRTC1 gene was found to be associated with seven aging and age-related disease outcomes (frailty index, LOAD, CHF, father’s age at death, mother’s age at death, breast, and endometrial cancer)." (PMID 40792619, 2025).
Infertility (2 papers, 2019 to 2021). "The absence of Crtc1 strikingly impaired the reproduction in mice even if not causing complete infertility." (PMID 33912553, 2021).